MIR378B (microRNA 378b)
Synonyms: hsa-mir-378b
Gene: MicroRNA gene on chromosome 3 (10,330,229 to 10,330,285, forward strand). Ensembl gene ENSG00000264534.
Homologues: Orthologues: chimpanzee MIR378B (100% identical), macaque mml-mir-378d (58% identical), mouse Gm54396 (47% identical), rat Mir3557 (47% identical). Paralogues in human: MIR378A (60% identical), MIR378D2 (49% identical).